MIR6745 (microRNA 6745)
Synonyms: hsa-mir-6745
Gene: MicroRNA gene on chromosome 11 (47,179,611 to 47,179,737, reverse strand). Ensembl gene ENSG00000275208.
Homologues: Orthologues: chimpanzee MIR6745 (100% identical).